KRAS (KRas proto-oncogene, GTPase)
Diseases named in the same sentence as KRAS in open-access papers (continued):
Sharing a sentence is not in itself a finding about the gene and the disease.
colon carcinoma (continued). "In contrast, KRAS mutations are usually progression events in colon cancers that follow a driver mutation in the Wnt signaling pathway." (PMID 36284306, 2022). "Taken together, our findings indicate that PCs play an important role in the malignant phenotype of colon CSCs and stem cell markers’ expression and highlight PCs repression, particularly of Furin, to target colon tumors with KRAS or BRAF mutation." (PMID 35267511, 2022). "The racial difference of KRAS mutation has been studied in colon cancer, where the highest KRAS mutation frequency was shown in Blacks than tumors from Whites and Asians." (PMID 36248982, 2022). "CfDNA and evDNA isolated from 30 blood samples of colon cancer patients with KRAS mutations were profiled using ddPCR." (PMID 36591510, 2022). "CNVs specific for MSS colon cancer IntOMICS identified edges from CNV to associated GE in five out of six genes of interest: KRAS, MYC, BIRC5, RAC3, and SMAD4." (PMID 35996085, 2022). "In a report based on the SEER database, KRAS mutations were found in approximately 23% of all stage IV colon cancers." (PMID 35523764, 2022). "Consistent with this possibility, we observed a lower number of KRAS mutations in high-BMI MSS colon cancer patients." (PMID 36046651, 2022). "Since one of the neoantigens identified from CRC tissue carried oncogenic KRAS (G12V), a major cancer driver mutation, we further explored neoantigens with oncogenic KRAS mutations in known colon cancer cell lines." (PMID 35982173, 2022). "In present study, we present two representative colon cancer patients with KRAS mutations who received individualized therapy using the PDX models." (PMID 36465411, 2022). "To explore the relationship between individual KRAS mutants and 249C sensitivity in vivo, we used a colon cancer (SW48) xenograft model with a set of colon cancer cell lines that differ in KRAS mutation status but are otherwise genetically matched." (PMID 35879364, 2022). "Other studies reported that KRAS mutation is associated with a poor prognosis in stage IV colon cancer." (PMID 35523764, 2022). "For example, hotspot mutations in KRAS can easily be tracked in cases where KRAS is involved with high prevalence, such as in pancreatic or colon cancer." (PMID 35307037, 2022). "An aberration in the KRAS gene is the most frequent type of driver mutation found in cancer, occurring in approximately 20% of all cancer cases and up to 40% of colon cancer cases." (PMID 36591510, 2022). "KRAS mutations are identified in approximately 90% of pancreatic cancers, 30–40% of colon cancers, and 15–20% of lung cancers, mostly non-small-cell lung cancer (NSCLC)." (PMID 35359599, 2022). "We provide evidence that CD3+/CD8+ lymphocytes from oligometastatic CRC patients display differential cytotoxicity against human colon cancer cells carrying KRAS mutations." (PMID 35936004, 2022). "The main pathogenesis of rectal cancer is the APC/β-catenin pathway, and the mutation frequency of KRAS and other genes in rectal cancer is higher than that in colon cancer, and the APC restrictive mode is more common." (PMID 35611168, 2022). "This phenomenon suggests a KRAS-linked mechanism that promotes colon tumour cell targeting to the lungs." (PMID 36111222, 2022). "KRAS mutation is thought to be the most common activating lesion in human tumors, especially pancreas, lung, and colon carcinomas, and is considered a predictor of poor patient outcomes." (PMID 33783985, 2021). "We observed a trend towards an increased basal expression of the NPM1 protein in BRAF-mutated colon cancer cell lines in comparison with the cells carrying either WT BRAF/mutant KRAS or double WT BRAF/KRAS." (PMID 34201061, 2021). "Between August 2016 and January 2017, 18 patients (50% men; median age 56.5 years) were enrolled; 72% had colon cancer and 56% had KRAS mutations." (PMID 33544407, 2021).
colon carcinoma (continued). "TAK1 inhibition suppresses inflammation and fibrosis in the colon, kidney, and lung and inhibits the in vivo growth of KRAS-mutated colon cancer cells and pro-survival signaling in breast cancer cells." (PMID 33824294, 2021). "In CRC, KRAS mutations are most associated with right-sided colon tumors and approximately 85% of KRAS mutations occur in one of three major hotspots (codons 12, 13 and 61)." (PMID 34742312, 2021). "The fourth subgroup consists of eight colon cancer models with KRAS mutations, and all of them are MSS." (PMID 34885128, 2021). "All PDX models with KRAS mutations tested in our study were resistant to treatment with cetuximab, confirming, in this case, the good predictivity of KRAS mutations as a biomarker for cetuximab in colon cancer patients." (PMID 34885128, 2021). "BRAF mutation, SMAD4 loss, and KRAS mutation are all associated with inferior survival among patients with colon cancer." (PMID 33874958, 2021). "Oxaliplatin has been shown to be ineffective in Kirsten rat sarcoma 2 viral oncogene (KRAS)-mutated colon cancers where SGs are prevalent." (PMID 33525628, 2021). "Female gender, left localization, classical adenocarcinoma, vascular invasion, presence of positive lymph node and advanced disease stage were found to be associated with KRAS mutated colon cancers as compared with KRAS wild-type colon cancers." (PMID 33784337, 2021). "Generally, the incidence of recurrence and death cases was significantly higher in KRAS-mutated colon cancers." (PMID 33784337, 2021). "KRAS exon 2-mutated colon cancers, compared with KRAS wild-type colon cancers were associated with the same clinicopathological features of RAS-mutated colon cancers." (PMID 33784337, 2021). "The association of KRAS/BRAF/MSI with invaded lymphatic spread pattern in colon cancer was assessed." (PMID 33484192, 2021). "When SGs are inhibited with cyclooxygenase 1/2 (COX1/2) inhibitors in KRAS-mutated colon cancers, researchers found that the cells were resensitized to oxaliplatin." (PMID 33525628, 2021). "Another study suggested that NOX1 (over)expression was correlated with KRAS mutations (G12Cys, G12Asp, G13Asp, G12Val, G60Gly, Q61Lys, Q61His) in human colon tumors and in KRASG12V transgenic mice in the intestine compared to adjacent normal colon tissue." (PMID 33691728, 2021). "Both uterine cancer and colonic cancer samples were examined for the presence of somatic mutations in the KRAS and NRAS genes in order to determine the clonality of the development of malignant neoplasms." (PMID 33937060, 2021). "In this study, farnesylthiosalicylic acid (FTS) was used to inhibit the activities of mutated KRAS in colon cancer SW480 cells to discover the potential link between KRAS activities and cancer-derived exosomes." (PMID 33466836, 2021). "For example, increased TOPO1 and ERCC1 expression, HER2/neu amplification, and KRAS mutation rates in rectal cancer compared with right- and left-sided colon cancer were reported." (PMID 34188197, 2021). "More KRAS mutated colon cancers had a higher incidence of metastatic disease at diagnosis (P = 0.04)." (PMID 33784337, 2021). "The presence of KRAS mutations not only affects prognostic survival, but also predicts the responsiveness of patients with colon cancer to epidermal growth factor receptor (EGFR) signaling inhibitors." (PMID 35118074, 2021). "Nine of 18 patients (50%) were male, and median age was 56.5 years; 13 patients (72%) had colon cancer, and 10 patients (56%) had tumors with KRAS mutations." (PMID 33544407, 2021). "For instance, one of the clinical challenges for EGFR targeted therapies is the KRAS gene mutation, so alternative approaches are needed to reduce failure in colon cancer therapy." (PMID 34707995, 2021).
colon carcinoma (continued). "Mutations in this gene and activated KRAS signaling are one of the most common causes of colon cancer development." (PMID 33671067, 2021). "Codons 12 and 13 of KRAS are hotspots for the mutations in several malignancies—lung, pancreatic, and colon cancer." (PMID 33669856, 2021). "In this context, we developed specific mAb recognizing the extracellular domain of human ASCT2 and examined the effects of mAb on in vitro and in vivo growth of KRAS‐mutated human colon cancer cells." (PMID 31709772, 2020). "Between 30 and 50% of colon tumors have mutations in the Kirsten-ras (KRAS) gene, which have a large nutritional attributable risk." (PMID 32723394, 2020). "In colon cancer, the KRAS gene was of high mutational frequency and rs121913529 was the most frequently mutated locus." (PMID 33254149, 2020). "Firstly, it lays the foundations to improve colon cancer treatment through optimal lipid lowering treatment in association with adjuvant chemotherapy in a subgroup of patients with KRAS mutated metastatic recto-sigmoid cancer." (PMID 32594310, 2020). "According to the presence of KRAS mutation, old age, females, and right-sided colon cancer patients were statistically predominant in the group with KRAS mutation." (PMID 33273596, 2020). "Some checkpoint-related genes (BTLA, CD80, CD86, CTLA4, IDO1, PDCD1LG2, and TIGIT) had decreased expression in the KRAS-mutated group, providing potential opportunities for immunotherapy in colon cancer." (PMID 33254149, 2020). "The concept of Ras dependency has conventionally been applied primarily in the context of tissues in which KRAS mutations are frequent, including pancreatic, lung and colon cancers." (PMID 32581224, 2020). "Activating KRAS was one of the most frequent oncogenic mutations in early colon cancer, recorded in 27–43% of patients." (PMID 33254149, 2020). "KRAS represents the third most frequently mutated gene in CRC patients (31% in colon cancer and 35% in rectal cancer)." (PMID 32580435, 2020). "Of the key genes, KRAS mutations are the most widely known, as they are mainly localized in codons 12 and 13, which were among the first linked to the pathogenesis of colon cancer, and have been found in about 42,6% of CRC cases worldwide." (PMID 32723394, 2020). "In conclusion, this study demonstrated that the Ab3‐8 anti‐ASCT2 mAb inhibits the tumor growth of colon cancer cells with KRAS mutation by inhibiting glutamine uptake." (PMID 31709772, 2020). "Effects of UAG are abrogated in (d) BRAF-transfected MCF7 cells, and (e) BRAF- and (f) KRAS-mutated colon cancer cells (6–12 replicates/group)." (PMID 32667883, 2020). "The prevalence of KRAS mutations was statistically significantly different by study country in left‐sided colon cancers (P = .003) and significantly different by study design among right‐sided tumors (P = .035)." (PMID 31856410, 2020). "The selected 299 mutations cover the National Comprehensive Cancer Network (NCCN) guideline of colon cancer recommended gene list relevant to treatment and prognosis, such as KRAS, NRAS, BRAF V600E mutations." (PMID 33008377, 2020). "Seven checkpoint-related genes (BTLA,CD80, CD86, CTLA4, IDO1, PDCD1LG2, and TIGIT) had decreased expression in the KRAS-mutated group, providing potential opportunities for immunotherapy in colon cancer." (PMID 33254149, 2020). "In order to explore the underlying mechanism of KRAS mutations in colon cancer, we performed GSEA to identify correlated pathways." (PMID 33254149, 2020). "In SW1116 and HCT116 human colon cancer cells with KRAS mutations, treatment with Ab3‐8 reduced intracellular glutamine transport, phosphorylation of AKT and ERK, and inhibited in vivo tumor growth of these cells in athymic mice." (PMID 31709772, 2020).
colon carcinoma (continued). "We evaluated the landscape of somatic mutations in colon cancer and found that KRAS mutations, particularly rs121913529, were frequent and had prognostic value." (PMID 33254149, 2020). "An in vitro study on colon cancer cells with KRAS mutations showed that vitamin C can partner with cetuximab to induce cell death depending on SVCT2 expression." (PMID 33352824, 2020). "Based on the gene mutational landscape in colon cancer, we found that KRAS mutations ranked in the top five of mutated genes in the TCGA and ICGC databases." (PMID 33254149, 2020). "There has been a renewed interest using high dose vitamin C potentially administered intravenous, as there is evidence that large doses of vitamin C can kill cultured colon cancer cells with BRAF or KRAS mutations by raising free radical levels." (PMID 32585852, 2020). "Future research should detail the mechanism of how KRAS mutation and its downstream signaling pathways alter the immune activities and clinical phenotypes of colon cancer." (PMID 33254149, 2020). "Although KRAS mutations mainly occur in pancreatic, lung, and colon cancers, Ras gene mutations and amplifications are also found in many other cancer types." (PMID 32581224, 2020). "Conversely, low levels of vitamin B12 intake were associated with reduced risk or KRAS mutations in a multicenter, case-control study of colon cancer." (PMID 32723394, 2020). "In a pooled analysis for stage II–III colon cancer, microsatellite instability, and KRAS and BRAF mutation status were used to construct a prognostic model in combination with TNM stage." (PMID 33335852, 2020). "Our findings are indicative of the prognostic and predictive value of KRAS and illustrate the relationship between KRAS mutations and immune activity in colon cancer." (PMID 33254149, 2020). "KRAS mutations were found to vary significantly by tumor side (P < .0001), with 46.3% (95% CI: 42.3%‐50.4%) of right‐sided colon cancers harboring a KRAS mutation compared to 35.8% (95% CI: 32.2%‐39.6%) of left‐sided tumors." (PMID 31856410, 2020). "Few research studies have systemically analyzed the effect of KRAS mutations on immune activity in colon cancer." (PMID 33254149, 2020). "A 68-year-old patient with KRAS-mutated advanced colon cancer, who received two prior lines of therapy in the palliative setting, was initially treated at DL7." (PMID 33216844, 2020). "BALB/c mice were inoculated with CT26 cells, a colon carcinoma cell line that is known to be homozygously mutated at KRAS G12D and sensitive to MEK inhibitor therapy." (PMID 31671149, 2019). "Genetic disruption of the mutant KRAS allele in human colon carcinoma cells resulted in decreased VEGF secretion." (PMID 31600989, 2019). "In one case of mutant stage II colon cancer (KRAS‐G12C), the G12D variant was detected in cfDNA instead." (PMID 31134762, 2019). "Since both HCT116 and HCT15 carry the G12D KRAS mutation, we wondered if the observed synergism of the combination was specific to KRAS-mutant colon cancer cell lines." (PMID 30674639, 2019). "The prevalence of KRAS missense mutations was much higher in patients with rectal cancer (21/35, ~60%) than in those with colon cancer (197/590, ~33%) (p = 2.9E − 03)." (PMID 31427573, 2019). "In APC-deficient colon cancers, KRAS-dependent cells specifically upregulate BMP signaling, which activates expression of TAK1/MAP3K7 and downstream transcriptional upregulation of canonical Wnt target genes." (PMID 31681559, 2019). "The ethanol extract of PBR has been shown to increase the cetuximab sensitivity of KRAS-mutated colon cancer in vitro and in vivo." (PMID 31717536, 2019). "The ethanol extract of PBR increased the sensitivity of cetuximab, a monoclonal antibody against KRAS-mutated colon cancer." (PMID 31717536, 2019). "In three isogenic colon cancer cell lines, researchers discovered that circRNAs are downregulated in cell lines containing the mutant KRAS allele compared with cell lines with the wild KRAS allele." (PMID 30925885, 2019).
colon carcinoma (continued). "Somatic mutations in KRAS are the most common activating lesions in human cancers, including pancreas, lung and colon cancers." (PMID 30833665, 2019). "MAPK1 siRNA inhibited CD137 expression consistently in human colon cancer HCT116 cell line harboring a mutated form of KRAS gene." (PMID 31288851, 2019). "The authors have found that high doses of vitamin C selectively killed colon cancer cells harboring mutated BRAF or KRAS through hyperaccumulation of its oxidized form, DHA, via GLUT-1." (PMID 30695991, 2019). "Eighty-three percent of liver metastases from right-sided colon cancers exhibited activating somatic mutations in KRAS, in contrast to 24% from left-sided cancers (P = 0.0005, Fisher’s exact test)." (PMID 29728604, 2018). "In colon cancer, Deb et al6 conducted a retrospective study of 652 patients with colon cancer and found that Rad21 expression is related to disease progression, showing a positive correlation with chemotherapy in tumors harboring KRAS mutations and resistance." (PMID 29797792, 2018). "In case of colon cancer, a previous study demonstrated that patients in stage II-IV of colon cancer with mutated KRAS were more likely to experience disseminated disease." (PMID 30509235, 2018). "The results showed that KRAS/NRAS/BRAF mutation rates in colon cancer were 44.2, 1.2, and 3.5%; in rectal cancer were 37.1, 4.3, and 0.7%; in gastric cancer were none, none and 2.9%." (PMID 30416987, 2018). "There are known molecular differences between right- and left-sided colon cancer with the former more often being poorly differentiated, as well as more often KRAS and/or BRAF mutated." (PMID 29334918, 2018). "A recent study explored the impact of KRAS mutations on the immune microenvironment among the various colon cancer consensus subtypes." (PMID 29652830, 2018). "KRAS gene mutation rate was significantly different in colon cancers (44.2%), rectal cancers (37.1%) and gastric cancers (0%), however, when colon cancer and rectal cancer were compared alone, the difference was not significant." (PMID 30416987, 2018). "This shift also allows AA to enter which leads to a disruption in the Warburg effect and a shutdown of the downstream KRAS pathway in mutated KRAS colon cancer cells." (PMID 30217071, 2018). "In particular, KRAS is the isoform prevalently mutated in pancreas, lung and colon cancer, while NRAS is the predominant isoform mutated in cutaneous melanomas and acute myelogenous leukemia and HRAS is the predominant isoform mutated in the bladder." (PMID 29534749, 2018). "Although the development of an alternative approach is in need for the patients with RAS mutations, more than 55–65% of colon cancer patients who express wild-type KRAS will still benefit from anti-EGFR therapies." (PMID 30158525, 2018). "The prognostic impact of KRAS mutation was recently analyzed in a large pool of colon cancer patient wild-types for the BRAF gene (to exclude from the analysis patients with mutated BRAF, who have a poor prognosis)." (PMID 29652830, 2018). "Compared with colon cancer and rectal cancer, KRAS and NRAS have a lower mutation rate in gastric cancer." (PMID 30416987, 2018). "In advanced stages of colon cancer, oncogenic mutations in KRAS lead to permanent KRAS activation, which in turn downregulates PPARγ and, consequently, SSAT expression and PA degradation." (PMID 30181486, 2018).